HSPB3 (heat shock protein family B (small) member 3)
Description:
Inhibitor of actin polymerization.
Synonyms: HSPL27; DHMN2C; HMN2C; HMND4
Tractability: No criterion of Open Targets' tractability assessment is met for any kind of drug.
Gene: Protein-coding gene on chromosome 5 (54,455,699 to 54,456,377, forward strand). Ensembl gene ENSG00000169271.
Subcellular location: Cytoplasm; Nucleus
Subcellular location (Human Protein Atlas): Nuclear speckles
Gene Ontology:
Biological process: response to unfolded protein
Cellular component: cytoplasm; nuclear speck; nucleus
Genetic constraint (gnomAD): Loss-of-function variants: 10 observed, 11.79 expected, observed/expected ratio (o/e) 0.85, 90% interval 0.52 to 1.43. The upper end of that interval is the gene's LOEUF score, 1.43, which puts it in group 5 of 6, group 1 being the genes least tolerant of losing a copy. Missense variants: 176 observed, 193.9 expected, observed/expected ratio (o/e) 0.91, 90% interval 0.8 to 1.03. Synonymous variants: 73 observed, 75.96 expected, observed/expected ratio (o/e) 0.96, 90% interval 0.8 to 1.17.
Homologues: Orthologues: chimpanzee HSPB3 (100% identical), macaque HSPB3 (96% identical), guinea pig HSPB3 (92% identical), rabbit HSPB3 (90% identical), pig HSPB3 (89% identical), rat Hspb3 (88% identical), mouse Hspb3 (87% identical), tropical clawed frog hspb3 (53% identical), zebrafish hspb3 (51% identical), Drosophila melanogaster CG14207 (24% identical), Drosophila melanogaster Hsp26 (23% identical), Drosophila melanogaster Hsp67Ba (23% identical), and 13 more. Paralogues in human: HSPB1 (30% identical), HSPB2 (30% identical), CRYAA (27% identical), CRYAB (25% identical), HSPB6 (25% identical), HSPB8 (23% identical), HSPB7 (17% identical), HSPB9 (16% identical).
Diseases named in the same sentence as HSPB3 in open-access papers:
HSPB3 is named in the same sentence as 48 diseases in open-access papers, as found by Europe PMC text mining. Sharing a sentence is not in itself a finding about the gene and the disease. The quoted sentences say what the papers report.
distal hereditary motor neuropathy (5 papers, 2018 to 2024). "Similar to BAG3 and HSPB8, mutations in the genes coding for DNAJB2, HSPB1 and HSPB3 have been associated with distal hereditary motor neuropathy (dHMN), including Charcot–Marie–Tooth disease." (PMID 40757567, 2023). "Four mutations in the HSPB3 gene have been linked to distal hereditary motor neuropathy (dHMN) and congenital myopathy, with unknown mechanisms." (PMID 33958580, 2021). "The first half of this paper will be focused on how mutations in HSPB1, HSPB3, and HSPB8 are linked to inherited peripheral neuropathies like Charcot-Marie-Tooth (CMT) disease and distal hereditary motor neuropathy (dHMN)." (PMID 32323160, 2020).
lung carcinoma (3 papers, 2009 to 2023). "The results showed that the prognostic value of METTL8 and HSPB3 was significantly available for lung cancer patients." (PMID 33816462, 2021). "Furthermore, lung cancer patients with tumors expressing high HSPB3 mRNA levels had a better prognosis, while the HSPB3 gene was strongly correlated with CD8+ T cell infiltration." (PMID 36768927, 2023).
neuropathies (3 papers, 2020 to 2022). "Dominant mutations in HSPB3 are a rare cause of neuropathy and myopathy: since the identification of first pathogenic HSPB3 mutation by Kolb and colleagues 10 years ago, only a few additional ones have been published." (PMID 32093037, 2020). "In this study, we explore the evolutionary history of four human sHSPs: HspB1, HspB3, HspB5, and HspB8, all known disease factors as mutant alleles have been found associated with various forms of neuropathies, myopathies, and with cataracts in the lens of the eye." (PMID 35678958, 2022). "HSPB3 mutations cause neuropathies and myopathies, but very few studies have linked HSPB3 to MNDs." (PMID 36233058, 2022).
amyotrophic lateral sclerosis (2 papers, 2023). Amyotrophic lateral sclerosis (ALS) is a neurodegenerative disease characterized by progressive muscular paralysis reflecting degeneration of motor neurons in the primary motor cortex, corticospinal tracts, brainstem and spinal cord. "Among the top hub genes associated with the common factor, TOB1, RANBP9, HSPB3, and SRSF3 were also linked to neurodegenerative disorders, such as Alzheimer’s disease, Parkinson’s, and amyotrophic lateral sclerosis, through various pathways." (PMID 36959830, 2023).
rhabdomyosarcoma (2 papers, 2021 to 2023). A rare aggressive malignant mesenchymal neoplasm arising from skeletal muscle. "HSPB3 Fragments Per Kilobase Million (FPKM) were significantly lower in FN-RMS compared to HSMM, indicating that HSPB3 expression is downregulated in rhabdomyosarcoma." (PMID 33958580, 2021). "In addition, HSPs such as HSPB3 can also promote the differentiation of rhabdomyosarcoma-derived cells, offering a potential therapeutic strategy (grey question marks)." (PMID 40757567, 2023). "Here, we studied whether HSPB3 exerts pro-differentiation functions using human myoblasts and rhabdomyosarcoma cells, which are myogenic cancer cells that fail to differentiate leading to malignant proliferation." (PMID 33958580, 2021). "In summary, our findings pave the way for a better understanding of HSPB3 implication in the neuromuscular system physiopathology, with implications that may extend to rhabdomyosarcoma." (PMID 33958580, 2021). "Nonetheless, our study supports a role for HSPB3 as a myoblast differentiation facilitator, with implications for disease, including rhabdomyosarcoma (where HSPB3 upregulation may have potential therapeutic value)." (PMID 33958580, 2021). "Remarkably, HSPB3 overexpression alone is sufficient to induce the differentiation of two human muscle cell lines, LHCNM2 cells, and rhabdomyosarcoma cells." (PMID 33958580, 2021). "To further test HSPB3 pro-differentiation effect, we used cells from fusion-negative rhabdomyosarcoma (FN-RMS), the most common soft tissue malignant tumor in children and adolescents, as a model of myogenic-derived cancer cells." (PMID 33958580, 2021).
alcohol dependence (1 paper, 2023). Physical and psychological dependence on alcohol. "HSPB3 has previously been linked to alcohol dependence and neurodegenerative disorders such as Alzheimer’s and Parkinson’s disease." (PMID 36959830, 2023).
axonal motor neuropathy (1 paper, 2022). "In addition, a new missense mutation in HSPB3 (R7S) has been recently identified in axonal motor neuropathy." (PMID 36213445, 2022).
bladder tumors (1 paper, 2023). "The noted downregulation of HSPB2 and HSPB3 mRNA expression levels in bladder tumors urged us to examine their potential association with the clinicopathological features of BlCa." (PMID 36768927, 2023). "Thus, HSPB2 and HSPB3 expression in bladder tumors and cell lines was assessed and their potential clinical significance concerning patients’ survival and disease outcome." (PMID 36768927, 2023). "Therefore, we then evaluated the clinical significance of the HSPB2 and HSPB3 genes expression levels in bladder tumor samples and matched adjusted normal bladder specimens." (PMID 36768927, 2023). "Given that the involvement of HSPB2 and HSPB3 genes in bladder tumorigenesis remains unclear, we herein analyze HSPB2 and HSPB3 gene expression levels in bladder tumors and matched adjacent normal urothelium." (PMID 36768927, 2023). "A significant downregulation of the HSPB2 and HSPB3 genes expression was observed in bladder tumors as compared to matched normal urothelium; yet, increased HSPB2 and HSPB3 levels were noted in muscle-invasive (T2–T4) vs. superficial tumors (TaT1), as well as in high-grade vs. low-grade tumors." (PMID 36768927, 2023). "Total RNA from 100 bladder tumor samples and 49 paired non-cancerous bladder specimens were isolated, and an accurate SYBR-Green based real-time quantitative polymerase chain reaction (qPCR) protocol was developed to quantify HSPB2 and HSPB3 mRNA levels in the two cohorts of specimens." (PMID 36768927, 2023).
Charcot-Marie-Tooth disease type 2 (1 paper, 2022). A Charcot-Marie-Tooth disease characterized by abnormalities in the axon of the peripheral nerve cell. "Mutations in HSPB1, HSPB8, and HSPB3 are implicated in inherited peripheral neuropathies (IPNs), such as Charcot-Marie-Tooth disease type 2 (CMT2) and distal hereditary motor neuropathies (dHMN)." (PMID 35328016, 2022).
distal hereditary motor neuropathy type 2 (1 paper, 2024). "Distal Hereditary Motor Neuropathy type 2 can be caused by any of four genes: HSPB8, HSPB1, HSPB3, or FBXO38 and affects fewer than one in a million people." (PMID 39480826, 2024).
lung squamous cell carcinoma (1 paper, 2023). "Moreover, it was recently reported that HSPB3 mRNA expression is upregulated in lung squamous cell carcinoma tissues compared with normal lung tissues based on the TCGA database." (PMID 36768927, 2023).
motor neuron degeneration (1 paper, 2023). "In fact, mutations in genes coding for several HSPs (e.g., HSPB1, HSPB3, HSPB8 and DNAJB6) are causative not only for myopathies, but also for distal hereditary peripheral neuropathies, which are characterized by motor neuron degeneration." (PMID 40757567, 2023).
muscular disease (1 paper, 2017). Myopathy is a peripheral nervous system disease consisting of any abnormal condition or disease of the muscular tissues; commonly designates a disorder involving skeletal muscle. "Conversely, mutations in small HSPs such as HSPB1, HSPB3, HSPB5, HSPB8 and the co-chaperones DNAJB6 and BAG3 have all been associated with motor neuron and muscular diseases." (PMID 28396624, 2017).
peripheral motor neuropathies (1 paper, 2022). "This is especially evident if HspB1, HspB3, and HspB8 are compared, all of them causing, when mutated, a similar spectrum of peripheral motor neuropathies." (PMID 35678958, 2022).
transitional carcinoma (1 paper, 2023). "Initial analyses revealed increased vs. human transitional carcinoma cells, expression levels of the HSPB2 and HSPB3 genes and proteins in high grade BlCa cell lines." (PMID 36768927, 2023).
myopathies (8 papers, 2020 to 2023). "The HSPB3 R116P mutation has been reported in a patient affected by myopathy with axonal neuropathy and in her father affected by mild neuromuscular symptoms." (PMID 35281256, 2022). "The HSPB3 A33AfsX50 (L34Ffs*50) frameshift mutation has been identified in a 70-years-old patient affected by myopathy." (PMID 35281256, 2022). "Two additional dominant HSPB3 mutations, p.L34Ffs*50 and p.R116P, were reported in patients with myopathy." (PMID 32093037, 2020). "HSPB3 mutations have been linked to neuropathies and myopathies." (PMID 35281256, 2022). "Finally, the HSPB3 p.Arg116Pro variant has recently been described in myopathy patients." (PMID 32397312, 2020). "The HSPB3 loss-of-function mutation excludes HSPB2-HSPB3 complex formation and causes aberrant HSPB2 phase separation that likely contributes to the myopathy." (PMID 32253739, 2020).
neuromuscular disease (6 papers, 2018 to 2022). "HSPB3 is a specialized chaperone involved in muscle cell differentiation, cytoskeletal remodeling, and protein degradation, and HSPB3 dysregulation causes neuromuscular diseases." (PMID 36553471, 2022). "To date, mutations in the genes coding for HspB1, HspB3, HspB5, and HspB8 have been associated with neuromuscular diseases." (PMID 34487489, 2021). "We propose that HSPB3 is a specialized chaperone engaged in muscle cell differentiation and that dysfunctional HSPB3 causes neuromuscular disease by deregulating LBR." (PMID 33958580, 2021). "Deregulation of this HSPB3 specialized function, due to gene silencing or disease-linked mutation (R116P-HSPB3), compromised myoblast differentiation, with implications for human neuromuscular diseases." (PMID 33958580, 2021). "Four of these sHSP genes carry known mutations which have been associated with neuromuscular disease phenotypes in humans: HspB1 (Hsp27, Hsp25), HspB3, HspB5 (αB-crystallin), and HspB8 (Hsp22), not counting polymorphisms or other sequence variants with unclear relation to disease." (PMID 35678958, 2022). "Furthermore, mutations R7S HspB3 and R116P HspB3 are associated with neuromuscular disease." (PMID 29969581, 2018). "In this review, we cover mutations in DNAJB6, DNAJB2, αB-crystallin (CRYAB, HSPB5), HSPB1, HSPB3, HSPB8, and BAG3, and discuss the molecular mechanisms by which they cause neuromuscular disease." (PMID 32093037, 2020). "Of the 10 sHSPs (or HSPBs) encoded by the human genome, four are currently known to be associated with neuromuscular disease; these are HSPB1 (Hsp27), HSPB3, αB-crystallin (CRYAB, HSPB5), and HSPB8 (Hsp22)." (PMID 32093037, 2020).
tumor (4 papers, 2009 to 2023). "More precisely, multivariate Cox models confirmed the unfavorable DFS of TaT1 patients under expressing HSPB2 (HR: 3.101; 95% CI: 1.134–8.484; p = 0.027) or HSPB3 (HR: 4.872; 95% CI: 1.322–17.96; p = 0.017), independently to tumor stage, grade, patient’s age and EORTC risk stratification." (PMID 36768927, 2023). "Consequently, the role of HSPB2 and HSPB3 in tumor progression could be associated with suppression of malignant cells spontaneous apoptosis." (PMID 36768927, 2023). "The pro-survival role of HSPB2 and HSPB3 in advanced tumor cells was also evident by our finding that HSPB2, HSPB3 genes expression silencing in high grade BlCa cells enhanced doxorubicin toxicity." (PMID 36768927, 2023). "Both HSPB2 and HSPB3 gene expression levels were upregulated in the advanced tumor grade cell line TCCSUP." (PMID 36768927, 2023). "Focusing on superficial tumors (TaT1), decreased HSPB2 and HSPB3 mRNA levels were correlated with a significantly higher risk for disease recurrence following TURBT, independently of tumor stage, grade, EORTC-risk group, and gender." (PMID 36768927, 2023). "Firstly, the expression levels of HSPB2 and HSPB3 genes were examined in BlCa cell lines of gradually increasing malignancy in order to evaluate their expression according to tumor grade." (PMID 36768927, 2023). "HSPB2 and HSPB3 gene expression levels were upregulated in advanced tumor grade cell lines." (PMID 36768927, 2023). "HSP-Clust II presents significantly higher levels of some HSPB genes such as HSPB2, HSPB3, CRYAA and CRYAB compared to the others HSP subtypes (a pattern that was also observed in Basal-like tumours)." (PMID 29954368, 2018). "The upregulation of HSPB3 expression in CRC patients was associated with poor RFS and OS regardless of their tumor stage or grade; therefore, this study suggested that HSPB3 is an excellent prognostic marker for CRC, regardless of clinicopathological prognosticators." (PMID 34831085, 2021).
peripheral neuropathies (2 papers, 2020 to 2022). "HspB1 harbored by far most of the mutations as compared to HspB3 and HspB8: In a systematic study of a cohort of 510 unrelated index patients with peripheral neuropathies, 32 patients were found to have mutations in sHSPs (32/510; 6.3%)." (PMID 35678958, 2022). "In this paper, we will first summarize how mutations in HSPB1, HSPB3, and HSPB8 cause hereditary peripheral neuropathies." (PMID 32323160, 2020).
HSPB3 also shares sentences with these, for which no sentence is quoted: cancer (5 papers); infection (2); adenocarcinoma (1); Alzheimer disease (1); autoimmune disease (1); Bladder Cancer (1); breast carcinoma (1); cardiac hypertrophy (1); cataract (1); Charcot-Marie-Tooth (CMT) disease (1); colorectal adenocarcinoma (1); congenital myopathy (1); COVID-19 (1); endothelial dysfunction (1); glioma (1); gouty arthritis (1); hyperuricemia (1); infectious disease (1); inflammatory bowel disease (1); lower respiratory tract disease (1); metastatic cancer (1); metastatic disease (1); multiple myeloma (1); myofibrillar myopathy (1); ovarian carcinoma (1); ovarian malignant tumor (1); Parkinson’s (1); prostate carcinoma (1); soft tissue malignant tumor (1).